CCL17 (C-C motif chemokine ligand 17)
Diseases named in the same sentence as CCL17 in open-access papers (continued):
Sharing a sentence is not in itself a finding about the gene and the disease.
colon cancer (10 papers, 2016 to 2025). "Indeed, CCL17/CCR4-dependent colon cancer cell migration is associated with increased activity of RhoA and can be inhibited by targeting Rho-kinase function." (PMID 28146427, 2017). "Using Apc1638N/+ CCL17-eGFP reporter mice, we found that TAMs and DCs upregulate expression of CCL17 in the microenvironment of small intestinal and colon tumors developing in Apc1638N/+ mice." (PMID 31681563, 2019). "Considered together, these findings suggest that miR-155-5p constitutes a pro-carcinogenic miRNA in serum starved colon cancer cells via promotion of RhoA signaling and migration in response to CCL17 stimulation." (PMID 28146427, 2017). "We found that miR-155-5p knockdown in serum starved colon cancer cells decreased CCL17-induced cell chemotaxis." (PMID 28146427, 2017). "Considering the key role of RhoA in cancer cell migration, it was of great interest to examine the role of miR-155 in CCL17-induced colon cancer cell migration in the present study." (PMID 28146427, 2017). "In summary, our data show that miR-155-5p positively regulates CCL17-induced RhoA activity and migration of serum starved colon cancer cells." (PMID 28146427, 2017). "We found that transfection with AntagomiR-155-5p abolished CCL17-induced colon cancer cell migration compared with control (ctrl) or AntagomiR ctrl." (PMID 28146427, 2017). "A recent study has shown that simvastatin potently inhibits CCL17-induced colon cancer cell migration." (PMID 26966430, 2016). "Treatment with conditioned medium of colon cancer cells increased macrophage expression of the M2-related markers arginase-1 (Arg1), CCL17, CCL22, IL-10 and IL-4." (PMID 27683110, 2016). "Knowing that CCL17-induced colon cancer cell migration is dependent on RhoA signaling, we next asked whether miR-155-5p might regulate CCL17-evoked activation of RhoA." (PMID 28146427, 2017). "Moreover, knocking down miR-155-5p markedly decreased CCL17-provoked activation of RhoA in colon cancer cells." (PMID 28146427, 2017). "Single cell RNA-sequencing revealed in vivo tumor cell-intrinsic CCL17 and CCL22 expression combined with expression from infiltrating classical resident and migratory dendritic cells in a CT26 colon cancer mouse tumor engineered to express LMP1." (PMID 35025968, 2022). "For example, it has recently been reported that colon cancer cells express CCR4, the receptor of CCL17, and that CCR4-CCL17 interactions mediate colon cancer cell migration." (PMID 28146427, 2017). "CCL17 is involved in colon cancer cell migration as well but has not shown to be significantly upregulated in our TAM‐like macrophages." (PMID 38037545, 2023). "Based on the considerations above, we hypothesized that should be added after hypothesized miR-155-5p might regulate CCL17-induced and CCR4-dependent migration of colon cancer cells via RhoA function." (PMID 28146427, 2017). "The expression of M2-like macrophage markers Arg1, MRC1 and IL-10, CCL17, and CCL22 were down-regulated, and the expression of M1-like macrophage markers iNOS, IL-12, and TNFa were induced by cetuximab in modeled TAMs, treated with CM of colon cancer cells in vitro." (PMID 34209679, 2021). "We found that AntagomiR-mediated knock down of miR-155-5p decreased CCL17-dependent cell migration without affecting colon cancer cell viability, suggesting that miR-155-5p is an important regulator of chemokine-induced directed colon cancer cell chemotaxis." (PMID 28146427, 2017).
lymphoma (10 papers, 2018 to 2025). A malignant (clonal) proliferation of B- lymphocytes or T- lymphocytes which involves the lymph nodes, bone marrow and/or extranodal sites. "In fact, a link between EBV infection and upregulation of CCL17/22 expression in lymphomas has been observed and mechanistically linked to the action of the viral latent membrane protein 1 (LMP1)." (PMID 35025968, 2022). "In fact, TARC/CCL17 protein expression was found to be significantly lower in HLA‐I+ compared to HLA‐I− cases when the analysis was restricted to EBV− lymphomas." (PMID 38836098, 2024). "In CTCL, extravasation of lymphoma cells into the skin is mediated by CCL17 and CCL22 released from epidermal cells." (PMID 29915722, 2018). "This high CCL17/22 and FOXP3 mRNA expression in EBV+ epithelial tumors is reminiscent of that in EBV+ lymphomas, but this could be due to different underlying mechanisms." (PMID 35025968, 2022). "Of note, CCR4, the receptor of TARC/CCL17 and CCL21, was also among the genes significantly downregulated in HLA‐I+ lymphomas." (PMID 38836098, 2024). "Of Note, the effect of downregulated CCL17/TARC and CCL22 was even detectable when the analysis was restricted to EBV+ lymphomas." (PMID 38836098, 2024). "Treg have been shown to be recruited to the TME via C-C motif chemokine ligand 17 (CCL17) and C-C motif chemokine ligand 22 (CCL22; herein described together as CCL17/22) that are expressed directly by some lymphomas or by infiltrating immune cells within the TME." (PMID 35025968, 2022). "In addition, LOAd703-infected lymphoma cells upregulated the secretion of several chemokines (CXCL10, CCL17, CCL22, CCL3, CCL4) essential for immune cell homing, leading to enhanced CAR T-cell migration." (PMID 33666760, 2021). "Therefore, consistent with previous studies, CCL17 and CCL22 expression appears to be exclusive to cHL primary tumor cells and cell lines and likely represents a specific feature of this lymphoma over ALCL." (PMID 31581676, 2019).
autoimmune disease (9 papers, 2013 to 2025). A disorder resulting from loss of function or tissue destruction of an organ or multiple organs, arising from humoral or cellular immune responses of the individual to their own tissue constituents. "The subsequent generation of Ccl17 mutant animals greatly helped to unravel the role of CCL17 in various infectious and autoimmune disorders." (PMID 29099057, 2017). "Similarly, to CCl17, osteopontin is a chemotactic factor binding to various surface receptors and is able to activate immune response due to infections, autoimmune diseases and tissue damage." (PMID 39329728, 2024). "Previous studies have shown that the CCL17/CCR4 receptor axis represents a group of potential new targets for the treatment and prevention of autoimmune diseases of the central nervous system." (PMID 33811453, 2021). "Chemokines such as CCL17, CCL23, and CXCL9 are frequently upregulated in autoimmune diseases." (PMID 40564127, 2025). "In addition to these cytokines, the results of the qPCR array also showed the expression levels of IL-6R, CCL17, and ACKR1, which are related to inflammatory responses or autoimmune diseases." (PMID 39771147, 2024). "As the biology of the CCL17/CCL22-CCR4 chemokine–receptor axis is being further elucidated, interest in its constituent molecules as potential therapeutic targets for the treatment of allergies, autoimmune diseases, and cancer has been growing." (PMID 29099057, 2017).
eczema (9 papers, 2019 to 2026). "In addition, we identified pathways and proteins-including TARC (thymus and activation-regulated chemokine)/CCL17-that were associated with pruritus and eczema severity." (PMID 41853463, 2026). "Serum IL-36β levels were not correlated with disease severity markers, such as serum lactate dehydrogenase, IgE, and CCL17 levels, eosinophil counts in peripheral blood, and the Eczema Area and Severity Index (EASI) scores." (PMID 37446281, 2023). "Although, within the INCA study, no increased risk was shown for doctor's diagnosed eczema after neonatal antibiotic treatment at 1 year of age, increased concentrations of Gal-3, CCL17 (TARC), and CCL18 (PARC) were detected within the infants with DDE." (PMID 31998285, 2019). "These cytokines, along with chemokines like CCL17 and CCL22, play a crucial role in recruiting and activating eosinophils and other immune cells, leading to the chronic inflammation and itchiness typical of eczema." (PMID 39670074, 2024).
osteoarthritis (9 papers, 2018 to 2025). A noninflammatory degenerative joint disease occurring chiefly in older persons, characterized by degeneration of the articular cartilage, hypertrophy of bone at the margins and changes in the synovial membrane. "GSK3858279, an anti-CCL17 monoclonal antibody, has shown efficacy in relieving osteoarthritis-associated pain, and CXCL9 inhibition has demonstrated therapeutic potential in ulcerative colitis." (PMID 40564127, 2025). "Furthermore, recent studies have broadened the role of CCL17 in osteoarthritis to include obesity-associated pain and disease." (PMID 41291326, 2025). "In collagenase-induced osteoarthritis, CCL17 expression in macrophages requires GM-CSF and IRF4, and CCL17 binding to CCR4 is required for pain." (PMID 41291326, 2025). "GSK3858279, a novel high-affinity human monoclonal antibody (mAb) that inhibits CCL17, has shown promise in clinical trials for osteoarthritis (OA) knee pain." (PMID 41291326, 2025). "Their research on gene-deficient mice showed that this pathway related to CCL17 plays an important role in the development of the disease; therefore, CCL17 can be considered a potential therapeutic target for the treatment of osteoarthritis." (PMID 35887379, 2022). "Studies on genetically deficient mice had shown that IRF4, CCL17 and CCR4 were essential for osteoarthritis pain, osteophyte size and optimal cartilage destruction." (PMID 31701394, 2019). "Furthermore, recent studies have indicated that the neutralization of CCL17, which is elevated in the synovial fluid in a mouse model of osteoarthritis, relieves pain." (PMID 32760393, 2020). "Therapy targeted CCL17 and JMJD3 ameliorated both pain and osteoarthritis." (PMID 31701394, 2019).
Pruritus (9 papers, 2016 to 2026). Pruritus is an itch or a sensation that makes a person want to scratch. "These pathways include cytokines, such as IL-4, IL-13, IL-31, and TSLP, and chemokines, such as CCL1, CCL13, and CCL17, which have been implicated in barrier disruption, pruritus, and immune cell recruitment in AD." (PMID 41583462, 2025). "Previous evidence showed CCL17 is associated with pruritus in MF, which is consistent with our finding that pruritus favors CD30+ TMF patients." (PMID 37790936, 2023). "Among the studied chemokines (C-C Motif Chemokine Ligand (CCL) 2/MCP-1, CCL3/MIP-1α, CCL4/MIP-1β, CCL5/RANTES, CXCL8/IL-8, CCL17/TARC, CCL18/PARC, CCL22/MDC), only CCL17/TARC showed a positive correlation with pruritus intensity." (PMID 37834183, 2023). "The serum concentration of CCL17/TARC correlated positively with pruritus assessed using the visual analogue scale (VAS) (R = 0.47; p = 0.05)." (PMID 36362116, 2022). "The analysis of the relationship between serum chemokine levels and disease severity as well as pruritus intensity, showed a positive correlation only in the case of CCL17/TARC for pruritus." (PMID 36362116, 2022). "It has also been reported that CCL17/TARC affects pruritus severity in AD patients." (PMID 37834183, 2023). "Possibly, CCL17/TARC levels could be used as a biomarker of pruritus severity, but studies on a larger group of patients are needed." (PMID 37834183, 2023). "The study indicated CCL17/TARC as a potential biomarker of pruritus intensity in PsO patients." (PMID 36362116, 2022). "It was reported that CCL17/TARC may contribute to pruritus in AD patients, as its serum levels positively correlated with VAS." (PMID 36362116, 2022). "However, we found that the serum concentration of CCL17/TARC in PsO patients correlated positively with the intensity of pruritus measured with VAS, and the p-value (p = 0.05) was on the borderline of statistical significance." (PMID 36362116, 2022). "Moreover, the presented study puts emphasis on the possible role of CCL17/TARC as a potential biomarker of pruritus intensity in PsO patients." (PMID 36362116, 2022). "The aim of the study was to analyse serum concentrations of CCL2/MCP-1, CCL3/MIP-1α, CCL4/MIP-1β, CCL5/RANTES, CCL17/TARC, CCL18/PARC, CCL22/MDC and CXCL8/IL-8, and their correlation with PsO severity and pruritus intensity." (PMID 36362116, 2022). "This may indicate the role of CCL17/TARC as a potential biomarker of pruritus intensity not only in AD, but also in PsO patients." (PMID 36362116, 2022).
lung carcinoma (8 papers, 2018 to 2024). "We found that TREM2 was strongly associated with CCL2, CCL3, CCL13, and CCL17 in lung cancer." (PMID 39135069, 2024). "Investigation of the relationship between CCL17 expression levels and survival outcomes in lung cancer patients using the Kaplan-Meier mapper database demonstrated that high CCL17 expression was significantly associated with favorable prognosis (OS, HR=0.79 (0.70-0.89), p=0.00012)." (PMID 39877375, 2024). "RT-qPCR analyses of CCL2, CCL3, CCL13, and CCL17 revealed that the transcription level of CCL2 in lung cancer was notably elevated compared to that in healthy lung." (PMID 39135069, 2024). "The relationship between expression levels of CCL17 and lung cancer patient survival was analyzed through the Kaplan–Meier plotter database." (PMID 35321241, 2022). "Correlation between CCL17 expression level and prognosis in lung cancer with different clinicopathological features by Kaplan–Meier plotter." (PMID 35321241, 2022). "With further studies on clinical characteristics of lung cancer patients, we found that CCL17 mainly affected the survival status of early-stage lung cancer patients." (PMID 35321241, 2022). "Marked changes in gene expression were measured for Ccl2, Ccl7, Ccl17, Ccl22, Ccl3, Ccl4, Il-1α, Il-1ß, and Il-1rn (inflammation), Lpo and Noxo1 (oxidative stress), and Mmp12 (inflammation/lung cancer)." (PMID 29463257, 2018). "Tumour cells, as well as tumour-associated macrophages and dendritic cells, produce high amounts of CCR4 ligands (CCL17 and CCL22) in breast, ovarian, and lung cancer patients." (PMID 38256152, 2024). "In human epithelial cells, including the HaCaT epidermal and Lc817 lung cancer cell lines, p63 positively regulates TARC/CCL17, a ligand of CCR4 that acts as a T-cell chemoattractant." (PMID 31340447, 2019). "We found that high expression of CCL17 had a good prognostic effect on lung cancer patients in the early stage (stages I–II), while it was not significant for patients with advanced lung cancer (stages III–IV)." (PMID 35321241, 2022). "Notably, the significant positive prognostic effect of CCL17 held true only for adenocarcinoma tissue among lung cancer types but not for squamous cell carcinoma." (PMID 35321241, 2022). "CCL17 high expression was significantly correlated with good prognosis of lung cancer patients at stage 1 (OS, HR = 0.59 (0.45–0.78), p = 0.00018; PFS, HR = 0.55 (0.36–0.85), p = 0.0064) but did not significantly correlate with OS and PFS in patients with lung cancer at stage 2–4." (PMID 35321241, 2022).
airway hyperresponsiveness (7 papers, 2011 to 2025). "We demonstrate that camel milk suppresses airway hyperresponsiveness, Th2 and Th17 cell recruitment, and associated cytokines (IL-4, IL-5, IL-13, IL-17A), while reducing dendritic cell activity and CCL17 expression in the lungs." (PMID 40577410, 2025). "Neutralizing either CCL22 or CCL17 has been shown to abrogate lung eosinophilia and airway hyperresponsiveness." (PMID 32586381, 2020). "It is reported that a number of chemokines such as CCL2, CCL5, CXCL10 are associated with RSV-induced airway hyperresponsiveness and CCL11, CCL17, and CCL 22 are involved in the development of pulmonary eosinophilia with RSV infection." (PMID 21980478, 2011). "CD86 siRNA treatment ameliorated OVA-induced airway eosinophilia, airway hyperresponsiveness, and the elevations of OVA-specific IgE in the sera and IL-5, IL-13, and CCL17 in the bronchoalveolar lavage fluid, but not the goblet cell hyperplasia." (PMID 25344652, 2014).
fibrosis (7 papers, 2019 to 2025). the formation of excess fibrous connective tissue in an organ or tissue in a reparative or reactive process. "Interestingly, serum CCL17 levels were lower in Fabp7−/− mice than in WT mice in both the CT and fibrosis groups." (PMID 40017805, 2025). "In addition, the Ccl17-KO mice displayed less cardiac fibrosis than the WT mice." (PMID 35687056, 2022). "Consequently, we measured the serum TGF-β and CCL17 concentrations in the CCl4-induced fibrosis model and CT mice (without CCl4)." (PMID 40017805, 2025).
ovarian carcinoma (7 papers, 2015 to 2024). A malignant neoplasm originating from the surface ovarian epithelium. "Conversely, the alternatively activated macrophages (M2) are the predominant macrophages in ovarian cancer and promote tumor growth through the secretion of immunosuppressive cytokines [e.g., IL-10, chemokine (C-C motif) ligand 17 (CCL17), CCL22]." (PMID 39802952, 2024). "An increased expression of CCL17 and CCL22 is consistent with the prognosis for patients with colon, lung, and ovarian cancers—the higher the expression of these chemokines in these tumors, the better the prognosis." (PMID 33182504, 2020). "Moreover, we analyzed the Cancer Genome Atlas Ovarian Cancer (TCGA-OV) database, and found CD68+YAP1low groups exhibited dramatically increased M2-like TAMs markers expression, such as MMP9, CCL8, SPP1 and CCL17, when compared to CD68+ YAP1high." (PMID 39198883, 2024). "Chronic hypoxia also enhances the effect of the described chemokines on cervical and ovarian cancer cells by increasing the expression of the CCR4, CCL17/TARC, and CCL22/MDC receptor, the latter of which are responsible for an increase in the proliferation of cancer cells." (PMID 32781743, 2020).
gastric cancer (6 papers, 2011 to 2025). A primary or metastatic malignant neoplasm involving the stomach. "In the comparison of metabolite interference group and M2 group marker proteins in gastric cancer cells, there were significant differences in CCL17, CCL18 and CXCL13." (PMID 39991579, 2025). "Similar results were seen in a gastric cancer model, in which elevated levels of CCL17 and CCL26 in the tumor microenvironment demonstrated a positive correlation with the frequency of Foxp3 Treg, which can bind both these ligands with its CCR4 receptor." (PMID 22112546, 2011). "Furthermore, the significant correlation between CCL17 or CCL22 chemokines and the number of tumor-infiltrating TReg cells was found in patients with neoplastic meningitis and gastric cancer." (PMID 22481922, 2012).
multiple sclerosis (6 papers, 2020 to 2024). A progressive autoimmune disorder affecting the central nervous system resulting in demyelination. "CCL17 is known to have inflammatory as well as regulatory functions and has been implicated in the pathogenesis of multiple sclerosis (MS)." (PMID 37408205, 2023). "Increasing evidence from clinical trials indicates the involvement of the CCL17/CCL22/CCR4 axis in the pathogenesis of multiple sclerosis." (PMID 36555280, 2022). "Cerebrospinal fluid levels of CCL22 and CCL17 are elevated in patients suffering from multiple sclerosis." (PMID 36555280, 2022). "Recent studies have demonstrated increased expression of CCL17 in patients suffering from diseases that produce pain symptoms, such as fibromyalgia, autoimmune encephalomyelitis, and multiple sclerosis." (PMID 32691345, 2020). "It has already been described that CCL17 levels are elevated in the serum of patients suffering from fibromyalgia and in the cerebrospinal fluid of patients with multiple sclerosis as well as in dendritic cells in an animal model of experimental autoimmune encephalomyelitis." (PMID 32760393, 2020). "In contrast, the levels of EGF (nominal P = 0.005), CCL17 (nominal P = 0.03) and CD40.L (nominal P = 0.03) did change in relapsing–remitting multiple sclerosis as well, implying that these proteins are not suitable as markers for conversion." (PMID 38978729, 2024).